EIF5AL1 (eukaryotic translation initiation factor 5A like 1)
Description:
Translation factor that promotes translation elongation and termination, particularly upon ribosome stalling at specific amino acid sequence contexts (By similarity). Binds between the exit (E) and peptidyl (P) site of the ribosome and promotes rescue of stalled ribosome: specifically required for efficient translation of polyproline-containing peptides as well as other motifs that stall the ribosome. Acts as a ribosome quality control (RQC) cofactor by joining the RQC complex to facilitate peptidyl transfer during CAT tailing step (By similarity). Also involved in actin dynamics and cell cycle progression, mRNA decay and probably in a pathway involved in stress response and maintenance of cell wall integrity (By similarity).
Synonyms: bA342M3.3; EIF5AP1
Tractability: Antibody: UniProt places it where antibodies can reach, with medium confidence; the Human Protein Atlas places it where antibodies can reach. PROTAC: ubiquitination databases record sites on it.
Gene: Protein-coding gene on chromosome 10 (79,512,533 to 79,516,440, forward strand). Ensembl gene ENSG00000253626.
Subcellular location: Cytoplasm; Nucleus; Endoplasmic reticulum membrane
Subcellular location (Human Protein Atlas): Cytosol; Plasma membrane
Gene Ontology:
Molecular function: translation elongation factor activity; ribosome binding; RNA binding
Biological process: translational elongation
Cellular component: cytoplasm; endoplasmic reticulum membrane; nucleus
Genetic constraint (gnomAD): Loss-of-function variants: 3 observed, 6.3 expected, observed/expected ratio (o/e) 0.48, 90% interval 0.22 to 1.23. That is too few expected variants to judge how well the gene tolerates losing a copy. Missense variants: 51 observed, 114.92 expected, observed/expected ratio (o/e) 0.44, 90% interval 0.35 to 0.56. Synonymous variants: 34 observed, 43.49 expected, observed/expected ratio (o/e) 0.78, 90% interval 0.59 to 1.04.
Homologues: Orthologues: mouse Eif5a (98% identical), macaque EIF5A (87% identical), rat Eif5a (86% identical), Drosophila melanogaster eEF5 (67% identical), Caenorhabditis elegans iff-2 (60% identical), Caenorhabditis elegans iff-1 (56% identical). Paralogues in human: EIF5A (98% identical), EIF5A2 (80% identical).
Diseases named in the same sentence as EIF5AL1 in open-access papers:
EIF5AL1 is named in the same sentence as 5 diseases in open-access papers, as found by Europe PMC text mining. Sharing a sentence is not in itself a finding about the gene and the disease. The quoted sentences say what the papers report.
breast carcinoma (2 papers, 2020 to 2026). "We have determined that besides its well-defined function in the p38-inflammatory pathway, MKK3 can induce MYC-dependent epithelial-to-mesenchymal transition in breast cancer patients in part through upregulation of EIF5A, EIF5AL1, and SNAI1 genes." (PMID 32873298, 2020).
colorectal cancer (2 papers, 2021 to 2023). A primary or metastatic malignant neoplasm that affects the colon or rectum. "Currently, the study of EIF5AL1 is next to nil, and only one study reported that EIF5AL1 was differentially expressed in patients with colorectal cancer metastasis." (PMID 37047039, 2023).
cancer (3 papers, 2020 to 2026). A tumor composed of atypical neoplastic, often pleomorphic cells that invade other tissues. "In order to investigate the function and molecular mechanisms of EIF5A1 and EIF5AL1 during cancer development and progression, we transfected the plasmids expressing EIF5A1 and EIF5AL1 in HeLa cells, respectively." (PMID 37047039, 2023). "The inconsistency between the expression level and the expected prognosis in the other five genes (RHPN1-AS1, MELK, EIF5AL1, and G6PC3: upregulated, but HR < 1; NLGN2: downregulated, but HR > 1) may be attributed to a protective response mechanism in order to resist the development of cancer." (PMID 32953881, 2020).
tumor (2 papers, 2023 to 2026). "Interestingly, although there are only three amino acid (at residues 36, 45, and 109) differences between EIF5A1 and EIF5AL1, we demonstrate that only EIF5A1 can be hypusinated while EIF5AL1 cannot, and EIF5AL1 has a tumor-suppressor-like function by inhibiting cell proliferation and migration." (PMID 37047039, 2023).
EIF5AL1 also shares sentences with these, for which no sentence is quoted: triple-negative breast carcinoma (1 paper).